CYP3A4 (cytochrome P450 family 3 subfamily A member 4)
Diseases named in the same sentence as CYP3A4 in open-access papers (continued):
Sharing a sentence is not in itself a finding about the gene and the disease.
tumor (continued). "Moreover, the specificity of miR-4277 for cyp3a4 was examined in our subcutaneous tumor model." (PMID 34381736, 2021). "Since CYP3A4 upregulation is an important mechanism of drug resistance, these observations suggest that the SXR transcription factor could play an important role in tumor escape to irinotecan treatment through the upregulation of CYP3A4 and drug detoxification." (PMID 21733184, 2011). "On the other hand, our analyses identified tumour suppressors like LHPP that inhibit growth, and CYP3A4 emerges as a favourable HCC prognostic marker." (PMID 41007296, 2025). "CYP3A4 and CYP3A5 transcripts and protein levels were higher in tumour tissue as compared with controls, but they were rather intermittent between patients." (PMID 38473371, 2024). "For now, it is important to incorporate what is currently known about CYP3A4, CYP3A5, CYP2C8, and ABCB1 into the assessment of a patient when the mTOR pathway is a desired target in treating a tumor." (PMID 37240915, 2023). "Based on predicted or known modulation of CYP3A4 and P-gp, DOAC should be cautiously used in case of co-treatment with many anti-tumor drugs, such as doxorubicin, abiraterone, enzalutamide, imatinib, and sunitinib." (PMID 37278934, 2023). "Conversely, WNK2, RUSC2, CYP3A4, and RGN, among the significantly downregulated genes in the non-tumor iP organoids, have been described as tumor suppressors downregulated in HCC." (PMID 34328417, 2021). "The expression levels of AR, CAT, CYP3A4, ESR1 and SLC10A1 were markedly upregulated in primary tumour tissues compared with normal tissues." (PMID 34717619, 2021). "All differentiation markers (CYP3A4, HNF4α and albumin) in infigratinib‐treated FGFR‐dependent tumours were significantly increased compared with their levels in vehicle‐treated tumours." (PMID 33179425, 2021). "In this study, we for the first time showed that LECT2, SLC10A1, CYP3A4, and HSD17B13 can suppress HCC tumor growth by inhibiting Warburg effect." (PMID 32576292, 2020). "Seven CYP450 genes including CYP1A2, CYP2A6, CYP2C8, CYP2C9, CYP2E1, CYP3A4, and CYP4A11 were downregulated in tumor tissues, which were validated in both GSE14520 and GSE36376." (PMID 30148168, 2018). "In our study, we found that several CYPs including CYP1A2, CYP2A6, CYP2C8, CYP2C9, CYP2E1, CYP3A4, and CYP4A11 were all downregulated in tumor tissues in HCC patients." (PMID 30148168, 2018). "Since PIP is an inhibitor of P-gp and CYP3A4 and it has been reported to enhance the bioavailability of several drugs, the effect of DTX-PIP combination was examined in mice with TxR tumor xenografts." (PMID 29423050, 2018). "CYP1A1 and CYP3A4 are capable of metabolizing a variety of carcinogens, such as polycyclic aromatic hydrocarbons, heterocyclic amines, nitrosamines, azo-dyes, and alkylating agents, and by doing so may produce active derivatives that lead to the tumor initiation." (PMID 29027980, 2017). "When comparing the relative mRNA concentration of CYP1B1, CYP2E1, CYP3A4, and CYP3A5 we detected in general higher regulation in tumor than their corresponding normal adjacent samples." (PMID 24699256, 2014). "In the present study, we compared the pattern expression of CYP1A1, CYP1A2, CYP1B1, CYP2E1, CYP2W1, CYP3A4 and CYP3A5 in paired tumor and normal tissue of child patients with RMS." (PMID 24699256, 2014). "Expression of AKR1C1, AKR1C2, AKR7A3, CYP3A4, and CBR1 was assessed by immunoblotting in protein lysates from tumor tissue samples of the independent pretreatment set of patients." (PMID 25526449, 2014). "Purified protein standards (CYP2B6, CYP2S1, and CYP3A4), MT-3 cells lysate (AKR1C2), human liver lysate (AKR1C1 and CBR1), and a pool of tumor samples (AKR7A3) were used as a calibrator for comparison of variability among membranes." (PMID 25526449, 2014).
tumor (continued). "Using real time quantitative RT-PCR, the gene expression pattern of CYP1A1, CYP1A2, CYP1B1, CYP2E1, CYP2W1, CYP3A4, and CYP3A5 were analyzed in tumor and adjacent non-tumor tissues from 13 child RMS patients." (PMID 24699256, 2014). "From this point of view, its interaction with CYP3A4 seems mainly related to total-body exposure gefitinib, while CYP1A1 is mainly responsible of its metabolism in tumor cells." (PMID 22111840, 2011). "Subclusters 2 and 8 exhibited high expression of the metabolic factors CYP3A4, OTC, PCK1 and TAT, suggesting that these genes may be involved in tumor cell metabolic reprogramming events." (PMID 38927691, 2024). "Similarly, another publication that included young patients claimed that the CYP3A4 enzyme was present in most soft tissue Ewing sarcoma patients (81%), while CYP3A5 and CYP3A7 tumour expressions were fainter, in that order." (PMID 38473371, 2024). "CYP2S1, CYP2U1 and CYP4X1 exhibited the highest percentage of strong immunoreactivity in contrast to other isoforms such as CYP2J and CYP3A4, which displayed no reactivity in majority of the tumours." (PMID 33809117, 2021). "Immunohistochemical analyses showed an absence of resistant colonies and an increase in CYP3A4 and albumin expression in drug combination‐treated tumours." (PMID 33179425, 2021). "For the castration-induced regression nadir group (i.e., those with the weakest or most unsuccessful castration-induced tumor regression), GSE1, CYP3A5, CTNNB1, CYP3A4, POU5F1, ABCB1, alkaline phosphatase liver/bone/kidney isozyme (ALPL), PROM1/CD133, ABCG2, and SOX2 were concomitantly upregulated." (PMID 34439112, 2021). "Tumours negative for the expression of CYP3A4 have been shown to have a better response rate to the antineoplastic drug docetaxel than those expressing the enzyme." (PMID 33809117, 2021). "Thus, the aim of the present study was to determine the mRNA expression pattern of seven representative CYPs (e.g., CYP1A1, CYP1A2, CYP1B1, CYP2E1, CYP2W1, CYP3A4, and CYP3A5) in paired tumor and normal tissue of childhood patients with RMS." (PMID 24699256, 2014). "The overexpression of CYP2W1, CYP3A4 and CYP3A5 in tumor tissues suggests that they may be involved in RMS chemoresistance; furthermore, they may be exploited for the localized activation of anticancer prodrugs." (PMID 24699256, 2014). "In conclusion, among other factors, the altered protein levels of certain CYPs (e.g. CYP2C8, CYP3A4 and CYP3A5) in colon mucosa might contribute to the development of neoplasia in the colon." (PMID 16281975, 2005). "The discussion focuses on the metabolic changes that occur with aging, its consequences for GGA availability, and the compensatory role of cytochrome P450 3A4 (CYP3A4), a hepatic enzyme that may partially substitute for MAOB in GGA synthesis but also potentially promotes tumor progression." (PMID 41142201, 2025). "In this context, elevated hepatic expression of CYP3A4 in aged or diseased individuals may inadvertently facilitate tumor progression rather than suppression." (PMID 41142201, 2025). "Both confluent and proliferating HepaFH3 cells (HepaFH3 C and HepaFH3 P) showed a statistically significant reduction in albumin, hepatocyte nuclear factor 4 alpha (HNF4A), and cytochrome P450 3A4 (CYP3A4) expression compared to non-HCC-PHHs isolated from tumor-free liver tissue." (PMID 40862732, 2025). "Among the CYP3A4 users group, a total of 10 patients exhibited no tumour." (PMID 37736819, 2023). "CYP3A4 activity can accelerate tumor progression that is independent of activation of oncogenes." (PMID 36359206, 2022). "In addition, we measured the expression of a number of other genes in the tumours including nuclear receptors (VDR, RXRα, SXR, ER α and β), cytochrome P450 enzyme (CYP3A4), proliferation marker (MCM2, CDC6, KI67), differentiation marker (sucrase isomaltase) and angiogenesis marker (CD31)." (PMID 26238339, 2016).
tumor (continued). "In the clinical trial of high doses of lapatinib conducted by Moasser and colleagues, it may be that the responses seen with lapatinib and ketoconazole were due to the ability of ketoconazole to inhibit ABCB1 in tumor, and not just CYP3A4 in the intestine." (PMID 26571496, 2015). "Although CYP3A4 and other CYP enzymes have been implicated in both systemic (by hepatic inactivation) and cell-intrinsic drug resistance, their role within the tumor microenvironment has never been studied." (PMID 25915157, 2015). "Therefore, our study aims to determine whether CYP3A4- and UGT1A9-mediated sorafenib metabolism is differentially affected in HCC patient tumor hepatic microsomes (THLMs) in comparison with those in adjacent normal hepatic microsomes (NHLMs) and commercial hepatic microsomes (CHLMs)." (PMID 24797816, 2014). "The comparisons between tumor tissue and normal tissue showed that PDE6G and CYP3A4 expression, but not CEL expression, in PCa tissue was considerably higher than that in normal prostate tissue." (PMID 38297388, 2024). "The expression levels of FCGBP, PABPC1 and NDRG1 were higher and the expression levels of ADH1A, CYP3A4 and ADH1B were lower in tumour tissues than in adjacent nontumour tissues." (PMID 35109839, 2022). "While studies investigating CYP3A protein expression in tumor samples have mainly found relatively high expression of both CYP3A4 and CYP3A5 both in tumor and non-tumor tissue." (PMID 31309254, 2019). "In the primary tumour samples from non-responder patients (N = 9), copy number alterations in CYP2C8 and/or CYP3A4 were detected more frequently than in the samples from responders (N = 8) (non-responders 6/9 vs. responders 1/8, p = 0.0498, Fisher’s exact test)." (PMID 37686184, 2023). "In addition, although not significant, a tendency of higher levels of CYP3A4 and CYP3A5 were found in the tumor tissue compared to the non-tumor tissue (mean: 1.02 versus 0.70, and 0.70 versus 0.43, respectively)." (PMID 24699256, 2014). "Although the metabolic activity and expression level of CYP3A4 and UGT1A9 were low exclusively in THLMs but not in NHLMs in our patients, the plasma concentrations of sorafenib and its metabolites probably depend on the volume of HCC tumor tissue and/or the surrounding cirrhotic tissue." (PMID 24797816, 2014).
myopathy (34 papers, 2003 to 2026). A disease of the muscle in which the muscle fibers do not function properly. "An example is the interaction between amiodarone (a CYP3A4 inhibitor) and statins (CYP3A4 substrates), which significantly increases the risk of myopathy." (PMID 40940774, 2025). "Studies on statin interactions demonstrated that simvastatin and lovastatin, as CYP3A4 substrates, resulted in an increased risk of myopathy when combined with inhibitors like cyclosporine A and mibefradil." (PMID 40722475, 2025). "The susceptibility to myopathy is greater in patients receiving concurrent therapy with a number of drugs, particularly those that inhibit CYP3A4, as well as with fibrates." (PMID 35005624, 2021). "This combination can result in increased plasma levels of CYP3A4 substrates such as simvastatin or atorvastatin, and statins are associated with myopathy and possibly impaired muscle function." (PMID 31671923, 2019). "Ranolazine has previously been linked to the development of statin-induced myopathy, because it also inhibits CYP3A4, which increases serum statin levels." (PMID 30131925, 2018). "Statins, metabolized by CYP3A4, may interact with tyrosine kinase inhibitors, raising the risk of myopathy or liver toxicity." (PMID 41153628, 2025). "Simvastatin and lovastatin are moderate-potency, lipophilic statins also metabolized by CYP3A4, which may increase the risk of myopathy when used with certain other medications." (PMID 40677502, 2025). "Moreover, CYP3A4 has been indirectly associated with myopathy in atorvastatin users due to its overrepresentation in these patients needing dose reduction or switching from atorvastatin to alternatives." (PMID 37759317, 2023). "Furthermore, additional risk factors not measured in this study may also affect blood statin levels and be relevant to myopathy risk (e.g. CYP3A4 inhibitors, thyroid disease, grapefruit juice)." (PMID 32702748, 2020). "While colchicine can inhibit the p-glycoprotein-mediated efflux transporter of statins and lead to myopathy, it is also a substrate of CYP3A4 enzymes, as are statins." (PMID 39130635, 2024). "· Evidence is weak for the use of colchicine· Bone marrow suppression, liver toxicity, diarrhea, myopathy, and serious drug interactions may occur with Cyp3A4 metabolites." (PMID 34844296, 2021). "A common side effect of statins is myopathy, and this complication can be exacerbated by the concomitant use of some other drugs, especially those that inhibit CYP3A4 as the cytoplasmic enzyme responsible for the metabolization of statins such as simvastatin, lovastatin, and atorvastatin." (PMID 35005624, 2021). "However, 20 % of the women in the myopathy group had a concomitant medication with a potential to inhibit CYP3A4, thereby increasing the plasma concentration of some statins." (PMID 27484241, 2016).
infection (27 papers, 2012 to 2025). The state of being infected such as from the introduction of a foreign agent such as serum, vaccine, antigenic substance or organism. "There we found that TLR2, IL6, OAT4, and CYP3A4 were significantly associated with the occurrence of infection." (PMID 33776761, 2021). "We found the polymorphic variant rs2242480 in the gene CYP3A4 that encodes the biotransformation enzyme CYP3A4 was related to the incidence of infection." (PMID 33776761, 2021). "Moreover, infection and inflammation are associated with down-regulation of hepatic and extra-hepatic expression and/or activities of P450, especially CYP3A4." (PMID 34899329, 2021). "We evaluated infection conditions to obtain maximum CYP3A4 expression using the recombinant Bac-Mam virus in COS-1 cells." (PMID 35295333, 2022). "In this study, we have applied a Bac-Mam system to introduce genes of drug-metabolizing enzymes into COS-1 cells and optimized infection conditions focusing on CYP3A4." (PMID 35295333, 2022). "Lopinavir and ritonavir are both CYP3A4 substrates, so there is a potential for elevated levels following infection and inflammation-related down-regulation of CYP3A4 expression." (PMID 35185562, 2022). "As it is known that the CMV promotor is a strong promoter in many cell types, we think that the difference in CYP3A4 expression levels among the 3 cell lines is a result of their sensitivity to infection by baculoviruses." (PMID 35295333, 2022). "CYP3A4 rs2242480C>T, SLC22A11 (OAT4) rs11231809T>A, TLR2 rs4696480T>A, and IL6 rs1800796C>G genetic polymorphisms are associated with the incidence of infections among patients undergoing cytotoxic chemotherapy." (PMID 33776761, 2021). "The main reason is associated with infection of SARS-CoV-2 elicitation a high production of cytokines including IL-1, TNF-α and IFN, which lead to down-regulate CYP3A4 and decrease elimination rate of LPV/RTV." (PMID 34899329, 2021). "The expression levels of CPS1, CYP2D6 and CYP3A4 proteins were significantly lower in the 43d M(+) cell group compared to the 1d M(+) cell group, suggesting that the extent of CPS1, CYP2D6, and CYP3A4 inhibition was related to the length of infection." (PMID 29075618, 2017). "The most significant reduction of CYP3A4 mRNA expression in PHH following infection with H. hepaticus at a MOI of 50 and 100 bacteria per hepatocyte was detected after 48 h (p = 0.001 and p<0.001, respectively) and 7 d (p<0.001 and p<0.001, respectively)." (PMID 24932686, 2014). "HNF1α transduction of CYP3A4 activity was found to be time-dependent and peaked at 7 days post-infection, after which point, the activity declined." (PMID 24733486, 2014). "Optimum infection conditions including the amount of Bac-Mam virus, culture days before collection, and concentration of sodium butyrate, an enhancer of viral-transduction were determined by monitoring CYP3A4 expression." (PMID 35295333, 2022). "We determined infection conditions by monitoring CYP3A4 expression." (PMID 35295333, 2022). "Thus, we prepared cell homogenates between 24 and 72 h post infection and quantified CYP3A4 expressions." (PMID 35295333, 2022). "Given their divergent response to the infection, we decided to use both Vero E6 and T84 cells as models for testing cobicistat and remdesivir, to obtain data on the efficacy of the drug combination and on its possible reliance on increased expression of either CYP3A4 or CYP3A5." (PMID 35229634, 2022). "In this regard, cell lines of gut origin and Vero E6 cells displayed a trend showing opposite expression patterns of CYP3A4 and CYP3A5 upon infection." (PMID 35229634, 2022). "While MBX-7591 exhibits inhibitory activity against the cytochrome P450 enzyme CYP3A4, this off-target activity is unlikely to interfere with a murine infection model." (PMID 38934618, 2024).
infection (continued). "According to the optimized infection condition, COS-1 homogenates were prepared, and the activity of expressed CYP3A4 was measured with luciferin-IPA as a substrate, which is converted to luciferin by CYP3A4 but shows minimal cross-reactivity with CYP3A5 and CYP3A7." (PMID 35295333, 2022). "In our study, baseline infection intensity and not CYP3A4, CYP2C19 and CYP2C9 genotypes was a significant predictor of adverse events following PZQ treatment." (PMID 34531744, 2021).
peripheral neuropathy (10 papers, 2016 to 2026). A disorder affecting the peripheral nervous system. "Kaplan-Meier analysis showed earlier onset of peripheral neuropathy and respiratory toxicity in CYP3A4 intermediate and poor metabolizers." (PMID 42072346, 2026). "However, our data suggest that CYP3A metaboliser phenotype (CYP3A4/CYP3A5) is not a risk factor with a large effect size for taxane-induced peripheral neuropathy." (PMID 37469869, 2023). "Concerning the CYP3A4, the rs35599367 SNP was significantly associated with exemestane concentration in postmenopausal BC patients, nor was it associated with dose reduction or peripheral neuropathy in paclitaxel-treated BC patients." (PMID 31477036, 2019).
renal disease (8 papers, 2009 to 2025). "NMV/r is contraindicated for co-administration with several drugs, including antiarrhythmic, anticancer, and anticonvulsant drugs, owing to its highly dependent CYP3A4 clearance, and dose adjustment is needed in patients with kidney disorders." (PMID 36992519, 2023). "In contrast, the clearance of the CYP3A4 probe substrate midazolam appeared to be unchanged in kidney disease patients." (PMID 32638224, 2020). "These metabolites may inhibit cytochrome P450 2C19 (CYP2C19) and cytochrome P450 3A4 (CYP3A4) reversibly, but as recent evidence suggests, they may also be involved in causing kidney disease." (PMID 32566351, 2020).
adenocarcinoma (5 papers, 2011 to 2023). A common cancer characterized by the presence of malignant glandular cells. "Besides, a published study has demonstrated induction of CYP3A4 and MDR1 mRNA in human adenocarcinoma LS180 cells by EVG." (PMID 28231276, 2017). "In treatment naïve adenocarcinoma samples, the copy number multiplication of paclitaxel-metabolizing CYP2C8 and/or CYP3A4 was more prevalent in non-responder patients with progressive disease/exit than in responders with complete remission." (PMID 37686184, 2023).
cardiovascular diseases (5 papers, 2016 to 2025). "Previous researches have demonstrated that CYP3A4 genetic mutation is associated with malignant diseases and cardiovascular diseases, which is in keep with the result of this study." (PMID 38117809, 2023). "The genetic mutation of CYP3A4*1G affects the activity of CYP3A4 and may be related to the susceptibility to cardiovascular disease." (PMID 38117809, 2023). "Lipid-Lowering Drugs and CYP3A4 Lipid-lowering drugs, particularly statins, are widely prescribed to reduce low-density lipoprotein cholesterol (LDL-C) and prevent cardiovascular diseases." (PMID 41011221, 2025).